NR5A1 (nuclear receptor subfamily 5 group A member 1)
Diseases named in the same sentence as NR5A1 in open-access papers (continued):
Sharing a sentence is not in itself a finding about the gene and the disease.
adrenocortical tumor (9 papers, 2013 to 2023). "Impaired steroidogenic factor 1 (NR5A1) activity plays a significant role in mutant Y1 mouse adrenocortical tumor cells." (PMID 36741260, 2023). "Overexpression of NR5A1/SF-1 inhibited multiple centrosomes during prolonged replication stress in adrenocortical tumor cells." (PMID 34208028, 2021). "NR5A1 is overexpressed in adrenocortical tumors, suggesting that NR5A1 relates to cancer development." (PMID 32093223, 2020). "SF-1, also known as Ad4-binding protein or NR5A1, binds as a monomer to nuclear receptor half sites on DNA, and it plays an important role not only in adrenal steroidogenesis but also in cell adhesion, cell proliferation, apoptosis, and angiogenesis of adrenocortical tumor cells." (PMID 33981288, 2021).
Obesity (9 papers, 2009 to 2024). Accumulation of substantial excess body fat. "While numerous studies in mouse models establish the role of SF-1 in metabolic regulation, limited data are available for DSD individuals with rare deleterious NR5A1/SF-1 variants and their association to obesity or overweight." (PMID 39479520, 2024). "The observed association of deleterious NR5A1/SF-1 variants with obesity supports the proposed involvement of SF-1 in regulating energy metabolism, beyond its role in reproductive function." (PMID 39479520, 2024). "Despite these limitations, our study proposes links between rare predicted deleterious missense NR5A1/SF-1 variants with obesity and adverse metabolic outcomes." (PMID 39479520, 2024). "Further research is needed to identify the possible sex hormone related or independent pathways linking NR5A1/SF-1 to obesity risk." (PMID 39479520, 2024). "There is limited previous evidence on the possible link between rare NR5A1/SF-1 variants and obesity in humans." (PMID 39479520, 2024). "In our study the association of rare NR5A1/SF-1 variants with obesity particularly in women, could be linked to sex-specific hormonal dysregulation, potentially rendering women with these variants more susceptible to obesity compared to men." (PMID 39479520, 2024). "Our study not only emphasizes the genetic association between rare predicted deleterious NR5A1/SF-1 variants and obesity but also underscores the need for more comprehensive research to bridge the translational gap between mouse models and humans, younger and older age, as well as sex differences." (PMID 39479520, 2024). "Primary hypothyroidism with negative antithyroid antibodies was diagnosed in one of the patients with a NR5A1 mutation when he was 12 years old (case 2); hearing loss due to middle ear infections, psychiatric problems, and obesity were also observed (one case each)." (PMID 25580123, 2014). "Through further protein domain association testing, we identified that women who carry rare deleterious missense NR5A1/SF-1 variants located in the DBD and LBD also have an elevated risk of obesity." (PMID 39479520, 2024). "One promising functional candidate within this region is sterogenic factor 1 (NR5A1), for which knock-out studies revealed elevated body weights related to late-onset obesity in mice." (PMID 26552583, 2015). "Notably, 32.3% of women who carried rare deleterious missense NR5A1/SF-1 variants located in the DBD and LBD had obesity, compared to 23% of noncarriers." (PMID 39479520, 2024).
adrenocortical carcinoma (8 papers, 2013 to 2023). "As experimental control, we used again Y1 adrenocortical cancer cells, where Nr5a1 gene down-regulation caused a reduction of Cyp11a1 mRNA expression." (PMID 23756599, 2013). "Furthermore, recent studies have indicated that NR5A1 is associated with adrenocortical cancer development." (PMID 32093223, 2020). "In adrenocortical carcinoma, NR5A1 controls cellular proliferation and maintenance likely through pathways independent of steroidogenic gene regulation." (PMID 35127484, 2021). "Our studies suggest the possibility of interaction between NR5A1 and ATF3 associated with cell proliferation in adrenocortical cancer cells." (PMID 32093223, 2020). "Moreover, E199A alone as well as combination with K194R enhanced NR5A1-mediated STAR protein levels in mouse adrenocortical cancer Y1 cells." (PMID 24232453, 2013). "Overexpression of the transcription factor NR5A1 and constitutive activation of canonical Wnt signalling leading to nuclear translocation of beta-catenin are hallmarks of malignancy in adrenocortical carcinoma (ACC)." (PMID 38155952, 2023). "However, more studies are needed to expand our understanding of how JDP2 coordinates with NR5A1 and FOXL2 to influence MC2R activity in adrenal glands and adrenocortical cancers." (PMID 28146118, 2017).
anorchia (8 papers, 2011 to 2025). "It has been suggested that NR5A1 is associated with bilateral anorchia, since one affected individual carried a heterozygous NR5A1 mutation (p.V355M)." (PMID 21853106, 2011). "The spectrum of genital anomalies in 46,XY DSD patients carrying NR5A1 variants comprises partial to complete gonadal dysgenesis with female external genitalia, genital ambiguity, penoscrotal hypospadias, micropenis, cryptorchidism, anorchia and male factor infertility." (PMID 37185284, 2023). "We included patients with anorchia in this study because the familial occurrence of anorchia and its association with other anomalies including gonadal dysgenesis suggest a genetic origin, but the genetic cause remains unknown, except in one case, which was reported to carry an NR5A1 mutation." (PMID 27899089, 2016). "We evaluated the clinical and biological presentation, and family histories of 26 boys with anorchia, and sequenced their SRY, NR5A1, INSL3, MAMLD1 genes and the T222P variant for LGR8." (PMID 21853106, 2011). "All patients with anorchia were sequenced for SRY, NR5A1, INSL3, MAMLD1 and the T222P variant of LGR8 and no pathogenic mutations were identified." (PMID 27899089, 2016).
ovarian failure (7 papers, 2011 to 2025). "Another heterozygous NR5A1 mutation (p.Pro129Leu) was identified in a patient with clitoral hypertrophy and ovarian insufficiency, detected by elevated FSH levels." (PMID 38785542, 2024). "NR5A1 gene mutations are also identified during puberty, primarily in girls with amenorrhea and ovarian failure." (PMID 38785542, 2024). "Women bearing NR5A1 defects should receive appropriate counseling and fertility guidance, enabling potential oocyte cryopreservation, due to the risk of developing ovarian insufficiency later in life." (PMID 28033660, 2016). "Patient 5's mother, who also carried the NR5A1 variant, developed ovarian insufficiency at 39 years." (PMID 28033660, 2016). "Finally, NR5A1 is associated with a wide spectrum of phenotypes including sex determination, XY sex gonadal dysgenesis, adrenocortical insufficiency, and ovarian failure." (PMID 38737775, 2023).
adrenal hypoplasia (6 papers, 2007 to 2021). "The second group is adrenal hypoplasia, including X-linked adrenal hypoplasia congenita (AHC) caused by NR0B1, adrenal hypoplasia caused by steroidogenic factor-1/NR5A1, IMAGe syndrome caused by CDKN1C and MIRAGE syndrome caused by SAMD9." (PMID 34193132, 2021). "Children (n = 22) who had been diagnosed with salt-losing forms of adrenal hypoplasia (19 isolated cases, 3 familial), and who were negative for mutations in DAX1 (NR0B1) and SF1 (NR5A1)." (PMID 17223989, 2007).
androgen insensitivity syndrome (5 papers, 2013 to 2022). Androgen insensitivity syndrome (AIS) is a disorder of sex development (DSD) characterized by the presence of female external genitalia, ambiguous genitalia or variable defects in virilization in a 46,XY individual with absent or partial responsiveness to age-appropriate levels of androgens. "The median PSAI score was similar to the control males in 5α-RD2, PAIS, and NR5A1 gene mutation groups (p > 0.05); while identical to the control females in complete androgen insensitivity syndrome (CAIS) and CYP17A1 gene mutation groups (p > 0.05)." (PMID 34627348, 2021). "Recently, some authors have reported heterozygous loss-of-function NR5A1 mutations in patients with clinical features of androgen insensitivity syndrome (AIS) and apparently normal Leydig and Sertoli cell function but without mutations in the androgen receptor gene (AR)." (PMID 24405868, 2014). "However, molecular analysis of SRD5A2 gene variants is generally required to confirm the diagnosis, since the hormonal and clinical profiles of 5ARD2 often overlap with other conditions, including androgen insensitivity syndrome, 17 beta-hydroxylase deficiency and defects in the NR5A1 gene." (PMID 31885560, 2019).
hypogonadism (5 papers, 2017 to 2025). A disorder characterized by decreased function of the gonads. "A male with a de novo heterozygous NR5A1/SF-1 variant (c.937C > T, p.Arg313Cys) (index case 14) presented with severely undervirilised external genitalia and hypogonadism at birth." (PMID 40037090, 2025). "NR5A1 (also named SF1) encoding the steroidogenic factor 1 is not only important for the formation of bipotential gonads and sex determination, but also involved in the pathogenesis of hypogonadism in mice." (PMID 28295047, 2017).
Anxiety (4 papers, 2014 to 2025). Intense feelings of nervousness, tension, or panic often arise in response to interpersonal stresses. "NR5A1 mutations have also been linked with anxiety and depression in humans." (PMID 28334933, 2017). "In addition, a recent clinical study from patients with SF1 (Nr5a1) gene mutations show psychiatric symptoms including excessive anxiety and/or depression, suggesting that SF1 and the VMH may have roles in both anxiety- and depressive-like behaviors." (PMID 25271967, 2014).
female infertility (4 papers, 2016 to 2021). Diminished or absent ability of a female to achieve conception. "For example, mutations in NR5A1 cause DSD as well as male and female infertility." (PMID 27899089, 2016).
germ cell tumor (4 papers, 2025 to 2026). A benign or malignant, gonadal or extragonadal neoplasm that originates from germ cells. "In contrast, a study on the so far largest international cohort of individuals with NR5A1 variants found only two patients (2/128, 1.6%) with gonadal germ cell tumors at the ages of 3 and 21 years, respectively." (PMID 39936125, 2025). "Although management follows the general principles applied to DSD with Y-chromosome material, only isolated cases of germ-cell tumors have been reported in NR5A1-related 46,XY DSD." (PMID 41303802, 2025). "Notably, the risk of germ cell tumors related to NR5A1 variants may be associated with the severity of the phenotype and variant type, and DHX37 variants may increase cancer risk when considering their function in ribosomal biogenesis, which warrants further investigation." (PMID 40290305, 2025).
Micropenis (4 papers, 2016 to 2024). "The spectrum of DSDs in 46,XY patients carrying NR5A1 mutations includes a range from partial to complete gonadal dysgenesis, genital ambiguity, penoscrotal hypospadias, micropenis, cryptorchidism, anorchia, or spermatogenic failure." (PMID 38785542, 2024).
Premature ovarian insufficiency (4 papers, 2019 to 2024). Amenorrhea due to loss of ovarian function before the age of 40.
primary adrenal insufficiency (4 papers, 2011 to 2023). A hormonal disorder that occurs when the adrenal glands fail to release adequate amounts of glucocorticoids (cortisol), mineralocorticoids (aldosterone, 11-deoxycorticosterone), and androgens (dehydroepiandrosterone) to meet physiologic needs, despite release of ACTH from the pituitary. "Initial attempts to find NR5A1 mutations in humans focussed on individuals with primary adrenal insufficiency and complete 46,XY gonadal dysgenesis, a phenotype resembling the Nr5a1 knock-out mouse." (PMID 21078366, 2011). "Importantly, the findings from the urinary steroid profiling analysis were instrumental in excluding other causes of primary adrenal insufficiency (i.e. mutations in NR5A1, StAR, CYP11A1 or HSD3B2)." (PMID 34524979, 2021). "In 1999, sequencing of NR5A1 in one patient showed for the first time that NR5A1 variants caused 46,XY DSD and primary adrenal insufficiency." (PMID 37189438, 2023). "NR5A1 variants do not affect adrenal functions in most cases; however, several variants have been identified in patients with primary adrenal insufficiency." (PMID 37189438, 2023).
adrenocortical insufficiency (3 papers, 2020 to 2024). An endocrine or hormonal disorder that occurs when the adrenal cortex does not produce enough of the hormone cortisol and in some cases, the hormone aldosterone. "Nr5a1/Sf-1 knockout mice have a sex reversal phenotype and adrenocortical insufficiency, while heterozygous Nr5a1/Sf-1 mice exhibit hypoplasia of the adrenal glands and testes." (PMID 39337600, 2024).
adrenoleukodystrophy (3 papers, 2007 to 2021). A peroxisomal disorder resulting in cerebral demyelination, axonal dysfunction in the spinal cord leading to spastic paraplegia, adrenal insufficiency and in some cases testicular insufficiency.
ovarian tumors (3 papers, 2013 to 2023). "Genotyping of three NR5A1 SNPs in matched tumor/normal tissues identified LOH in 16/36 (44%) of the ovarian tumors successfully analyzed, and somatic mutations (gain of allele) in 10% of the tumors." (PMID 23291911, 2013). "This fact together with the finding of LOH at this locus in 44% of the ovarian tumors, strongly suggest a high somatic mutation frequency of the NR5A1 gene in ovarian cancer." (PMID 23291911, 2013). "The finding of somatic NR5A1 gene mutations (gain of allele substitutions) in 10% of the ovarian tumors is striking, given the fact that we interrogated only three base pairs of the NR5A1 gene in these assays (the three SNP positions)." (PMID 23291911, 2013). "Therefore, the frequently observed genetic (LOH/substitution) events at the NR5A1 locus may significantly contribute to the reported loss of SF-1 protein in ovarian tumor tissue." (PMID 23291911, 2013). "The majority of the ovarian tumors had a single LOH event at the NR5A1 locus (out of maximum three possible), but 5 tumors (14%) showed multiple LOH events." (PMID 23291911, 2013). "This analysis should include the NR5A1 gene promoter, since SF-1 protein expression is lost in both human ovarian tumors and tumor cell lines." (PMID 23291911, 2013). "The existence of both genetic and epigenetic NR5A1 gene abnormalities in ovarian tumors further suggest that SF-1 is a common and important target in ovarian carcinogenesis." (PMID 23291911, 2013). "To probe for the prevalence of LOH at the NR5A1 locus, we genotyped matched ovarian tumor and normal FFPE tissue DNA samples from the same ovarian cancer patient, for three NR5A1 gene SNPs: rs2279605, rs10120967 and rs7851737." (PMID 23291911, 2013). "This analysis indicated that 36 out of 46 (78%) ovarian tumors had appreciable NR5A1 methylation (2nd, 3rd and 4th quartile of methylation levels), and 17/46 (37%) had high levels of NR5A1 methylation (3rd and 4th quartile of methylation levels)." (PMID 23291911, 2013). "We thus decided to examine the degree of LOH in ovarian tumors, specifically at the NR5A1 locus and report LOH in 44% of the tumors." (PMID 23291911, 2013). "Specifically, the data demonstrate that most ovarian tumors contain genetic and/or epigenetic alterations at the NR5A1 locus, significantly more frequently compared to normal ovaries." (PMID 23291911, 2013). "Thus we examined the methylation status of the NR5A1 gene promoter in ovarian tumors, and report significantly higher prevalence of NR5A1 gene methylation in ovarian tumors compared to normal (i.e. non-tumor) ovaries." (PMID 23291911, 2013). "Thus the genotyping data show frequent genetic (LOH/substitution) events at the NR5A1 locus in ovarian tumors." (PMID 23291911, 2013). "Thus, ovarian tumor tissues display significantly more frequent NR5A1 gene methylation than normal ovarian epithelial tissues." (PMID 23291911, 2013). "Furthermore, a methylation-sensitive restriction enzyme method was used to demonstrate statistically significant (p<0.0001) increase in the frequency of NR5A1 gene methylation in ovarian tumors (36/46; 78%) versus normal ovaries (1/11; 9%)." (PMID 23291911, 2013). "These somatic NR5A1 substitutions were present in 10% of ovarian tumors." (PMID 23291911, 2013). "Thus, LOH occurs frequently at the NR5A1 locus in ovarian tumors." (PMID 23291911, 2013). "We compared the bulk transcriptomes of hiPSCs, COV434 and KGN ovarian tumor cells, and sorted FOXL2+CD82+ granulosa-like cells from day 5 of a polyclonal differentiation with expression of our previously identified top TFs (NR5A1, TCF21, GATA4, and RUNX1)." (PMID 36803359, 2023). "However, the fact that the 37% of the ovarian tumors that show high methylation (++ or higher methylation level) display >57% of the band intensity of β-actin, suggests that a significant proportion of the NR5A1 gene is methylated in these ovarian tumors in vivo." (PMID 23291911, 2013).
ovarian tumors (continued). "The cumulative data also demonstrate that 62% of the ovarian tumors have LOH, high level of methylation, or both at the NR5A1 locus." (PMID 23291911, 2013). "In conclusion, we report frequent somatic alterations of the NR5A1 locus in ovarian tumors, including LOH, base substitution, and methylation of the NR5A1 gene promoter." (PMID 23291911, 2013). "Furthermore, we detected both a high level of NR5A1 gene methylation and LOH in 21% of the ovarian tumors that we analyzed." (PMID 23291911, 2013). "Retrospective analysis of the clinical data suggest that presenting stage and histologic grade of ovarian tumors are not significantly affected by the presence of somatic NR5A1 gene alterations (Table I and data not shown)." (PMID 23291911, 2013). "To that effect, the detection of both a high level of NR5A1 gene methylation and LOH in 21% of the ovarian tumors that we analyzed, may partially explain this loss." (PMID 23291911, 2013). "Furthermore, Kaplan-Meier survival curves were similar for both ovarian tumors with and without NR5A1 gene alteration (LOH/methylation; data not shown)." (PMID 23291911, 2013).
pituitary adenomas (3 papers, 2020 to 2022). "In the present work we carried out proteomic and transcriptomic analyses to identify altered genes related to splicing events in pituitary adenomas derived from POU1F1 and NR5A1 cell lineages." (PMID 33261069, 2020). "Consistent with the histologic differentiation, the M6 pituitary adenoma showed massive upregulation of POU1F1 and PITX1, high overexpression of PITX2 and NR4A1-3, but minimal or absent expression of TBX19 and NR5A1, respectively." (PMID 35978432, 2022). "The pituitary adenomas derived from POU1F1- and NR5A1-cell lineages as well as the non-tumoral gland share a total of 1780 proteins." (PMID 33261069, 2020).
Primary amenorrhea (3 papers, 2010 to 2023). "We and others previously reported that pubertal virilization and also isolated primary amenorrhea should orient towards a diagnosis of 46,XY sex reversal related to NR5A1 alterations (MIM #612965)." (PMID 37855374, 2023).